IL10 (interleukin 10)
Diseases named in the same sentence as IL10 in open-access papers (continued):
Sharing a sentence is not in itself a finding about the gene and the disease.
pneumococcal infection (continued). "The levels of BAL IFN-β, IFN-γ, and IL-10 were also determined after the pneumococcal infection in infant mice treated with liposomes." (PMID 32660087, 2020). "IL-10 modulates pulmonary inflammation that occurs in the context of pneumococcal infection by constraining the expression of TNF-α, IFN-γ, and IL-6." (PMID 29990318, 2018). "The different respiratory immune environment (such as the levels of IFN-β, IFN-γ, and IL-10 in the lungs) on C. pseudodiphtheriticum-treated mice at the moment of pneumococcal infection would induce an improved immune response and protection." (PMID 28878760, 2017). "In terms of anti-inflammatory cytokines, we and others have shown that levels of IL-10 were significantly increased after secondary pneumococcal infection." (PMID 29326698, 2017). "Streptococcus pneumoniae infection led to massive cytokine and chemokine increase in both the cerebral cortex and spleen homogenates of wild-type mice (except expression of IL-10 in cortex)." (PMID 28615695, 2017). "The work showed that the treatment of mice with blocking anti-IL-10 antibodies before secondary pneumococcal infection resulted in reduced bacterial cell counts in lungs and prolonged survival." (PMID 28848552, 2017). "In this sense, IL-10 plays a key role in the modulation of the immune response induced after pneumococcal infection, limiting the inflammatory immune response and stimulating antibody production." (PMID 21834957, 2011). "IL-10 attenuates the proinflammatory cytokine response and its absence hampers effective clearance of the infection, and reduces survival of pneumococcal infection." (PMID 20195541, 2010). "Kinetic analysis of responses beyond 72 h postinfection will be important in future studies to determine whether the abrogation of neutrophil responsiveness to IL-10 has a longer-term impact on recovery from pneumococcal infection." (PMID 37381945, 2024). "Our data thus indicate that the improved production of IL-10, IL-27, and IL-6 by AMs of 040417-treated infant mice may play an important role in limiting inflammation during the pneumococcal infection by increasing the protective functions of Treg cells." (PMID 34207076, 2021). "Considering that the assay performed required 1x106 neutrophils per mouse, which represent around of 10% of the total neutrophils found in lungs during pneumococcal infection, it is possible that the amount of IL-10 producing neutrophils required to prevent inflammatory infiltration is higher." (PMID 33995357, 2021). "Therefore, reduction of IL-10 during a secondary pneumococcal infection may be beneficial for the host." (PMID 29326698, 2017). "In addition to IL-10 production, the T regulatory cells induced in response to pneumococcal infection might mediate immune regulation and the suppression of pathological inflammatory responses through a direct cell-cell contact mechanism." (PMID 22563306, 2012). "Thus, we considered that IL-10 induction by PppA+LcV and PppA+LcM would favor the humoral specific immune response and would regulate the inflammatory response after pneumococcal infection; low IL-10 levels would compromise regulation of the host defense response against infectious challenge." (PMID 21834957, 2011). "Pneumococcal infection can enhance the concentrations of TNF, IL-1β, IL-6, IFN-γ, and IL-10 in the respiratory tract and blood of immunocompetent well-nourished mice, while in protein-malnourished the levels of those immune mediators are significantly lower." (PMID 40507039, 2025). "The concentrations of IFN-γ and IL-17 as well as of the immunoregulatory cytokines IL-10 and IL-27 were determined in BAL samples after the pneumococcal infection." (PMID 34207076, 2021).
pneumococcal infection (continued). "utilized FMT in a mouse model of gut microbiota depletion and demonstrated that lung bacterial counts, as well as levels of tumor necrosis factor-α (TNF-α) and interleukin-10 (IL-10), returned to normal levels in FMT-colonized mice within six hours following pneumococcal infection." (PMID 40861492, 2025). "In addition, the depletion of AMs abolished the reduction of lung injuries and the enhancement of the respiratory IL-10 production induced by NV1505 or PG1505 in both the primary and secondary pneumococcal infections." (PMID 32660087, 2020). "Furthermore, inhibiting IL-10 resulted in an increase in CCL3 and CCL5, two of the chemokines that were increased in aged mice following pneumococcal infection." (PMID 25595646, 2015). "In the absence of IL-10, a marked increase in pro-inflammatory cytokines is induced during pneumococcal infection." (PMID 20195541, 2010). "Our results showed that the production of KC, MIP-2, IL-10, IL-6, and IL-1β did not significantly change when bacterial loads were similar in the lungs of dually infected mice and S. pneumoniae-infected mice after pneumococcal infection at 7 dpi." (PMID 33722928, 2021). "In addition, the production of IL-10, IL-6, and TNF-α did not significantly change, notably in contrast to IL-1β, which was significantly enhanced after pneumococcal infection at 14 dpi in our study." (PMID 33722928, 2021).
Sjögren’s syndrome (35 papers, 2012 to 2025). "Additional genetic polymorphisms reported to be associated with risk for Sjögren’s syndrome include variants of interleukin 10 (IL-10), tumor necrosis factor (TNF), antigen peptide transporter 2 (TAP2), and 2′-5′-oligoadenylate synthetase 1 (OAS1)." (PMID 30626116, 2019). "Regulatory B cells produce IL‐10, which restrains the T follicular helper cell activities in patients with primary Sjögren's syndrome." (PMID 39679991, 2024). "Our previous studies reported that butyrate inhibits RA progression by regulating HDAC 8 in T cells and suppresses Sjögren’s syndrome by regulating IL-10-secreting B cells." (PMID 37496081, 2023). "For the treatment of Sjögren’s syndrome, Interleukin-10 (IL-10), interleukin-17 (IL-17), and vasoactive intestinal peptide (VIP) genes were also transferred to mice." (PMID 26331060, 2014). "The aim of the study was to characterize and to enumerate peripheral IL-10--producing B cells, Tregs and pDCregs in primary Sjögren's Syndrome (pSS) patients in regard of their clinical and serologic activity." (PMID 23800367, 2013). "In addition, CXCL13 strongly correlates with local pathology in Sjögren’s syndrome patients and elevated IL-10 levels in plasma and saliva correlate with disease severity and autoantibody titres." (PMID 34839819, 2021). "Notably, Sjøgren’s Syndrome (SS) has been associated with overexpression of proinflammatory cytokines, including TNF-α, IL-7, IL-1β, IL-6, IL-10, IL-17, IL-18 and gamma-interferon (γ-IFN)." (PMID 29997338, 2018). "However, whether IL-27 participates in pathological progress of Sjögren syndrome (SS) through regulating CD4+IL-10+ T cells remains unknown." (PMID 32849596, 2020). "The study aimed to quantify certain cytokines involved in the pathomechanism of primary Sjögren syndrome (IL2, IL5, IL6, IL10, IL13, TNFα, IFNγ) and determine their common clinical correlation." (PMID 36143051, 2022). "For instance, in patients with Sjögren’s syndrome, TFH cells are critically restrained by IL-10-producing regulatory B cells (Breg)." (PMID 33572870, 2021). "Previous studies on a subset of B cells with modulatory properties in patients with RA, primary Sjogren’s syndrome (SjS), and SLE have demonstrated a hyperfunction in these B cells anti-inflammatory cytokines like IL-10 production and eventually homeostasis." (PMID 33198645, 2020). "Decreased expressions of IL-6, IL-10, and IFN-γ were also observed for purified protein derivative-stimulated PBMC in patients with Sjogren’s syndrome with myalgia." (PMID 23245186, 2012). "Negative correlations have been observed between IL10-producing regulatory B cell numbers and disease activity in patients with Sjögren’s syndrome." (PMID 39337678, 2024). "Additionally, there were two false positive cases of GBM and brain involvement of Sjögren's syndrome in the 4‐marker (CXCL13, IL‐10, β2‐MG, and sIL‐2R) and 3‐marker (CXCL13, IL‐10, and β2‐MG) algorithms." (PMID 32314548, 2020).
vitamin D deficiency (35 papers, 2011 to 2026). A nutritional condition produced by a deficiency of VITAMIN D in the diet, insufficient production of vitamin D in the skin, inadequate absorption of vitamin D from the diet, or abnormal conversion of vitamin D to its bioactive metabolites. "A higher prevalence of vitamin D deficiency (79.5% vs. 59.4%, P = 0.000315) and lower IL-10 levels (6.84 vs. 9.04 pg/ml, P < 0.0001) were observed in the patient group compared to healthy controls." (PMID 40630332, 2025). "In a study conducted to consider the immunomodulatory properties of vitamin D, it was found that the TNF-α levels were normal and the IL-10 levels were low in CD patients with vitamin D deficiency." (PMID 38623153, 2024). "Our results suggest that vitamin D deficiency is associated with increased RL, the pro-inflammatory Th2 and Th17 responses, and the regulation of the T-reg production of IL-10 in clinical and pre-clinical models." (PMID 36793727, 2023). "Studies have shown that perinatal vitamin D deficiency in mice can lead to a reduction in Treg cells that secrete IL-10 and an increase in Th2 cells." (PMID 37760982, 2023). "If the direct effect of vitamin D deficiency on cytokine regulation precedes the Aβ increment, the suppressed anti-inflammatory cytokine, such as IL-10, can be interpreted as enhancing Aβ accumulation." (PMID 36009371, 2022). "Consistent with a previous report, we found that vitamin D deficiency reduced IL-10, which is an anti-inflammatory cytokine, and this was further supported by the association with increased Aβ." (PMID 36009371, 2022). "IL-10, which is an inflammatory cytokine released by activated microglia, was also reduced by vitamin D deficiency in the early and late stages." (PMID 36009371, 2022). "Vitamin D deficiency in utero and in early life has been linked with increased Th2 lymphocytes and reduced T regulatory cells and interleukin (IL)‐10, leading to macrophages and dendritic cells producing proinflammatory cytokines." (PMID 35763390, 2022). "After adjusting for possible confounders, not having knowledge about vitamin D foods, taking fewer vitamin D foods, and higher levels of IF-γ and IL-10 were associated with a higher risk of having vitamin D deficiency." (PMID 34221502, 2021). "In fact, neonates with vitamin D deficiency develop a Th2-skewed pulmonary immune phenotype and reduced IL-10-secreting T regulatory cells affecting neonatal pulmonary function." (PMID 27987538, 2016). "Peri-natal vitamin D deficiency alone has immunomodulatory effects including Th2 skewing and reduced IL-10-secreting T regulatory cells, exaggerated with additional allergen exposure." (PMID 24943330, 2014). "Correcting vitamin D deficiency may help enhance IL-10 levels, leading to improved treatment outcomes." (PMID 40630332, 2025). "Furthermore, these researchers observed that serum levels of IL-10 trend towards higher levels in subjects with vitamin D deficiency." (PMID 36071429, 2022). "Moreover, consistently with previous studies, not knowing vitamin D foods, taking fewer vitamin D foods, and higher levels of IF-γ and IL-10 were associated with higher chances of having vitamin D deficiency." (PMID 34221502, 2021). "Furthermore, vitamin D deficiency was associated with a pro-inflammatory profile (determined by the IL-6 to Interleukin-10 (IL-10) ratio)." (PMID 25954901, 2015). "Correcting vitamin D deficiency may improve IL-10 levels and enhance treatment outcomes." (PMID 40630332, 2025). "Moreover, this mode of supplementation could improve the clinical response to IFX, especially for those with vitamin D deficiency and high disease activity, probably via up-regulating IL-10 expression." (PMID 34746207, 2021). "Vitamin D supplementation increases the levels of anti-inflammatory cytokines (IFN-γ and IL-10) in subjects with normal weight and vitamin D insufficiency." (PMID 38276294, 2023).
vitamin D deficiency (continued). "This study also demonstrated the effect of vitamin D deficiency on increased circulating INF-γ and Il-10 interleukins." (PMID 34281061, 2021). "Neonatal mice that had in utero and early-life vitamin D deficiency had significantly increased pulmonary CD3+CD4+T1ST2+ cells and reduced CD4+IL-10+ cells." (PMID 24943330, 2014). "Third, long-term vitamin D insufficiency and deficiency cause secondary hyperparathyroidism, which in turn may mediate many of the detrimental CV effects including increasing systemic inflammation, as indicated by increased levels of C-reactive protein, homocysteine, and interleukin-10." (PMID 25528383, 2014). "Vitamin D deficiency leads to diminished production of inflammatory cytokines, including IL-1, IL-6, IL-12, IL-21, and TNF-α, while enhancing the production of anti-inflammatory cytokines, such as IL-10." (PMID 39598148, 2024). "Differentiation and recruitment of Th17 and IL-10 producing CD4+ T cells was not affected by vitamin D deficiency." (PMID 38567749, 2024). "Inflammatory cytokines (IL-6, IL-10, CRP, etc) are elevated in Vitamin D deficiency." (PMID 27417476, 2014). "It has been reported that vitamin D deficiency reduces the downregulation of nuclear factor-κB activity, subsequently leading to a pro-inflammatory state, with an increase in pro-inflammatory cytokines IL-6 and TNF-α and a decrease in anti-inflammatory cytokine IL-10." (PMID 39544568, 2024). "Various inflammatory diseases have been associated with vitamin D deficiency and a study suggested that vitamin D inhibits monocyte pro-inflammatory cytokines like TNF-alpha and IFN-gamma induction by increasing the production of anti-inflammatory cytokine like IL10." (PMID 38439034, 2024). "As observed previously with higher doses of OVA/Alum, vitamin D deficiency enhanced the capacity of ADLN cells to proliferate and secrete cytokines like IL-4, IL-5, IL-10 (data not shown), but not IL-6, IL-17, TNF or IFNγ (data not shown)." (PMID 23826346, 2013).
gastritis (34 papers, 2007 to 2025). Inflammation of the stomach. "The high levels of cytokines release, like TNF-a (Tumor necrosis factor-a), IL-6 (interleukin-6), and IL-10 (interleukin-10) caused by aspirin ingestion are critical in the acute phase of inflammation and severity of gastritis." (PMID 37184667, 2023). "In the case of gastric infection, previous work had found that complement depletion decreased the severity of Helicobacter felis induced gastritis in an IL-10 deficient mouse model." (PMID 36973281, 2023). "We previously found that increased gastritis in IL-10−/− mice is associated with decreased H. pylori colonization, similar to our findings here in tgIFN-γ mice." (PMID 33443133, 2020). "Polymorphisms in the promoter of the gene encoding the tumor necrosis factor (TNFα-308) and interleukin 10 (IL-10) (IL-10-592 and -1082) also have an important role in the development of gastritis associated by H. pylori infection." (PMID 28512631, 2017). "Similarly, feeding an A2AAR agonist to IL-10 deficient mice suffering from gastritis due to H. pylori attenuated gastritis and lowered TNF-α and IFN-γ in the gastric mucosa, but led to increased bacterial colonization." (PMID 25950510, 2015). "IL-10 has also been correlated with HP+ gastritis, where immunosuppressive CD19+IL-10+ B cells were found to be significantly higher in HP-positive patients compared to uninfected patients." (PMID 39193325, 2024). "Of which, MMP9, CXCL2, CXCL8, and IL-10 were part of the 15 common genes, and these four genes are significantly upregulated between gastritis patients and normal control." (PMID 34471638, 2021). "IL-10 is an important cytokine involved in reducing H. pylori-induced gastritis and is therefore a particularly important Treg effector at mucosal surfaces." (PMID 26657504, 2016). "Conversely, the gene expression levels of IL-10 messenger RNA (mRNA) were significantly higher in the H. pylori(+) (Hp[+]) gastritis group than in the control group (P<0.01)." (PMID 26087062, 2015). "The current study also identified that the children of GCA patients as having a higher prevalence of IL-10-819 as TT and IL-10-592 as AA than DU, compatible with previous findings to show such genotypes with lower IL-10 excretion and more severe gastritis." (PMID 25884934, 2015). "The Th2 cytokine IL-10 can down-regulate the host immune response by modulating the Helicobacter-specific Th1 immune response and reducing the severity of gastritis induced by H. pylori." (PMID 22526791, 2012). "PTGS2, NOS2, EGFR, MMP9, CXCL2, CXCL8, and IL-10 may be the important direct targets of Weibing Formula 1 in gastritis treatment." (PMID 34471638, 2021). "Just as loss of T4SS function and cagY recombination do not occur in immunodeficient mice, they occur more commonly when the immune response is increased in IL-10 knockout mice, which have more severe gastritis and lower bacterial load when challenged with H. pylori." (PMID 33443133, 2020). "Increased levels of IL-10 may contribute to the chronicity of gastritis, however, this regulatory cytokine is of fundamental importance to prevent mucosal injury mediated by the inflammatory response." (PMID 32230910, 2020). "Exogenous E2 supplementation showed a protective effect against the development of HP-induced gastritis and premalignant lesions via several mechanisms such as stimulation of IL-10 activity, enhancement of Th2-mediated immune responses, and inhibitory effects on epithelial cell proliferation." (PMID 30779804, 2019). "For example, increased production of pro-inflammatory cytokines in the mucus (such as IL-1, IL-6, IL-10, TNF-α, and interferon-γ) of those who are at risk of H. pylori infection is associated with gastritis induced by H. pylori and the severity of inflammation." (PMID 30320011, 2018).